NLRP3 (NLR family pyrin domain containing 3)
Diseases named in the same sentence as NLRP3 in open-access papers (continued):
Sharing a sentence is not in itself a finding about the gene and the disease.
atherosclerosis (continued). "The NLRP3 inflammasome, an innate immune-signaling complex, regulates CASP1 activation and the subsequent processing of pro-IL-1β, triggers vascular wall inflammatory responses and leads to the progression of atherosclerosis." (PMID 32054994, 2020). "According to other reports IL-1β and NLRP3 are not involved in atherosclerosis development, while IL-1α has a key role." (PMID 32545788, 2020). "Cholesterol crystals that accumulate in the arterial wall during atherosclerosis, monosodium urate (MSU) accumulation in joints leading to gout and hydroxyapatite crystals triggering rheumatoid arthritis all activate the NLRP3 inflammasome." (PMID 32849554, 2020). "NLRP3 inflammasome can be activated by cholesterol crystal and is essential for atherogenesis, and has been proven to be required for VSMC calcification in atherosclerosis." (PMID 30941060, 2019). "Considering the link between PAF/PAF-R and activation of the NLRP3 inflammasome, further research is required to discern whether PAF also activates the NLRP3 inflammasome in atherosclerosis." (PMID 31816871, 2019). "Different from increased CD36 and activated NLRP3 inflammasome induced by LDL and ox-LDL in atherosclerosis and foam cell formation, high-level triglycerides and FFAs conduct CD36-mediated lipid accumulation, NLRP3 inflammasome activation, and podocyte injury of ORG." (PMID 31097920, 2019). "It is possible that NLRP3-mediated alterations of hematopoiesis and atherosclerosis are regulated in a local rather than a systemic way." (PMID 31712595, 2019). "NLRP3 inflammasome contributes to the development of a wide variety of human diseases, including gout, atherosclerosis, neurodegenerative diseases and type 2 diabetes (T2D), but the medications targeting NLRP3 inflammasome are not available in clinic." (PMID 29531021, 2018). "This compound targets the inflammasome by inhibiting NLRP3 oligomerization and ASC recruitment and may offer a safe and selective therapeutic benefit to patients with atherosclerosis in future." (PMID 29997514, 2018). "After analyzing NLRP3−/−, ASC−/−, or caspase-1−/− on Apoe-null mice fed with a high-fat diet for 11 weeks, the team observed no significant change in cell infiltration, plaque stability, and atherosclerosis progression." (PMID 29850631, 2018). "LMP is known as an important activating signal for the NLRP3 inflammasome, because activation of the NLPR3 inflammasome in various chronic inflammatory disorders, such as gout, atherosclerosis, and diabetes mellitus, takes place as a consequence of lysosomal disintegration." (PMID 30136196, 2018). "Moreover, several inflammasome components NLRP3, ASC and IL-1β are elevated at the gene expression level, in a diabetic porcine model of atherosclerosis." (PMID 29515457, 2018). "Higher expression of NLRP3, AIM2, and ASC could give rise to IL-1β and IL-18 secretion, promoting atherosclerosis and further destabilizing atherosclerotic plaques, which indicates their importance in cardiovascular disease pathogenesis." (PMID 30555415, 2018). "Until date, we have deduced that the NLRP3 inflammasome contributes significantly to the pathological process of atherosclerosis, cardiac I/R injury, and other nonischemic cardiac diseases." (PMID 29850631, 2018). "This indicates a mechanism in atherosclerosis that does not implicate necessarily participation of the NLRP3 inflammasome." (PMID 28950870, 2017). "The reasons for these discrepancies are unclear, but suggest that inflammation in atherosclerosis does not always require the NLRP3-inflammasome." (PMID 24686534, 2014).
atherosclerosis (continued). "Dysregulated NLRP3 inflammasome activation leads to an imbalance between these systems and the release of inflammatory factors that mediate metabolic disorders, such as obesity, type 2 diabetes mellitus (T2DM), and atherosclerosis, through autocrine or paracrine mechanisms." (PMID 40830103, 2025). "Furthermore, we demonstrated that vulnerable psEVs promoted endothelial inflammation and atherosclerosis, partially through the delivery of miR‐497‐5p and subsequent suppression of UCP2, thereby activating the ROS/TXNIP/NLRP3 pathway, a well‐established mechanism of NLRP3 activation." (PMID 40391195, 2025). "Additionally, the non-canonical NF-κB pathway triggers NLRP3-inflammasome-mediated endothelial pyroptosis and atherosclerosis via activating caspase-1 and GSDM-D in human aortic endothelial cells." (PMID 39770410, 2024). "As interest in the application of NLRP3 inhibitors for CVD gains momentum, it becomes increasingly important to address the research gap concerning the activation of the NLRP3 inflammasome in other atherosclerosis-relevant cell types, including cell-specific blocking strategies." (PMID 37830572, 2023). "Notably, the inhibitor of NLRP3 inflammasome, MCC950, was able to block ox‐LDL‐induced pyroptosis, suggesting that MCC950 could be used as a promising treatment for atherosclerosis." (PMID 37125240, 2023). "Thus, in atherosclerosis, impaired CMA may mediate the pathological process of the disease by reducing the degradation of NLRP3 inflammatory vesicles." (PMID 37655052, 2023). "Therefore, exploring inhibitors of the inflammatory regulators such as NLRP3 might represent a promising strategy for the treatment of NAFLD and atherosclerosis." (PMID 37198205, 2023). "However, only AIM2 was overexpressed and AIM2, but not NLRP3, deletion attenuated accelerated atherosclerosis in these mice, pointing to a more relevant role of the AIM2 inflammasome in this model." (PMID 38035089, 2023). "Interestingly, also independent of atherosclerosis, cholesterol metabolism and the NLRP3 inflammasome appear to be functionally related." (PMID 37239938, 2023). "Given that OR6A2 lies upstream of the NLRP3 inflammasome, OR6A2 could serve as a potential therapeutic target for inflammation initiated by lipid, especially, for the prevention, treatment, and reversal of atherosclerosis." (PMID 35864109, 2022). "Furthermore, Wang and colleagues demonstrated that LPS/ATP activation of NLRP3 inflammasome stimulates HMGB-1 release leading to cholesterol accumulation in VSMCs and foam cells formation during atherosclerosis, through the downregulation of LXRa and ABCA1 expression." (PMID 36244983, 2022). "The negative effect of NLRP3 on atherosclerosis is mainly dependent on its effector cytokine IL-1β." (PMID 35647057, 2022). "Excessive activation of the NLRP3 inflammasome and subsequent release of IL-1β have been shown to play a major role in the occurrence, development, and complications of atherosclerosis, acute myocardial infarction, non-ischemic injury to the myocardium, and heart failure." (PMID 34381021, 2021). "NLRP3 is not the only pathway through which atherosclerosis and COVID-19 interact." (PMID 34522180, 2021). "However, another study showed that atherosclerosis in ApoE−/− mice is not dependent on the NLRP3 inflammasome." (PMID 33535473, 2021). "Therefore, this study showed that the progression of atherosclerosis was independent of the activation of NLRP3-mediated inflammation." (PMID 32378144, 2021).
atherosclerosis (continued). "BA inhibited macrophage NLRP3 inflammasome via TGR5 signaling-mediated ubiquitination to ameliorate HFD-induced glucose intolerance and insulin resistance, highlighting the coordination of microbiota and immune response to regulate metabolic diseases and further atherosclerosis." (PMID 33227973, 2020). "Activation of the NLRP3 inflammasome has been extensively investigated in macrophages and atheroma cells, including smooth muscle cells (SMC), endothelial cells (ECs), and T cells, each of which play significant roles in onset and development of atherosclerosis." (PMID 32226786, 2020). "Limited studies have evaluated the role of the NLRP3 inflammasome in the pathogenesis of irradiation-induced atherosclerosis, but the role of the NLRP3 inflammasome has been extensively studied in non-irradiation-induced atherosclerosis." (PMID 32226786, 2020). "Last but not least, interference with the key components of the NLRP3 inflammasome could become another therapeutic approach to atherosclerosis." (PMID 32664349, 2020). "It is yet an unanswered question if NLRP3 inflammasome mediates the JNK and ASK-induced apoptosis, or whether at the lower intensity of stimuli the NLRP3 inflammasome apoptotic role saves against atherosclerosis development." (PMID 32664349, 2020). "However, to the best of our knowledge, the fucoidan-mediated regulation of NLRP3 inflammasome has not previously been reported in atherosclerosis." (PMID 33505579, 2020). "Additionally, the NLRP3 inflammasome and its related proteins are not CNS specific, as the NLRP3 protein has been shown to be elevated in systemic inflammatory disorders including type 2 diabetes, atherosclerosis, and steatohepatitis." (PMID 32252777, 2020). "In this study, we first confirmed the potent anti-atherogenic efficacy of Tan IIA using ApoE-/- mice—a well-established murine atherosclerosis model and then further investigated whether and how Tan IIA inhibits oxLDL-induced NLRP3 inflammasome activation in macrophages." (PMID 33290264, 2020). "Deletion or inhibition of the NLRP3 inflammasome complex, including NLRP3, ASC, or IL-1β, was shown to improve lipid metabolism, and to decrease inflammation, pyroptosis, and infiltration of more immune cells into plaques, thus ameliorating inflammatory responses and atherosclerosis progression." (PMID 32751530, 2020). "In addition, a recent study established a causal link between NLRP3-mediated overproduction of IL-1β and the development of atherosclerosis in a ten-eleven translocation 2 (TET2) mutant mouse model, which could be abrogated by an NLRP3 inflammasome inhibitor." (PMID 30279971, 2018). "However, such phenomena could be reversed by silencing NLRP3, indicating that OGG1 is indeed a negative regulator of atherosclerosis." (PMID 29850631, 2018). "It is possible that for the formation of small CC in the artery walls, the signaling is not strong enough to reach a sustained inflammation, which may account for the lack of involvement of NLRP3 in atherosclerosis." (PMID 29896195, 2018). "In metabolic diseases, the expression of NLRP3 inflammasome will increase, and now more and more evidence suggests that NLRP3 inflammasome plays an important role in many noninfectious inflammatory diseases, such as gout, atherosclerosis, and diabetes." (PMID 28182085, 2017). "Indeed, previous reports suggest that the development of atherosclerosis development was attenuated in the absence of NLRP3 inflammasomes." (PMID 29259717, 2017). "Additionally, we detected NLRP3 inflammasome production in THP-1 cells stimulated with PMA, which imitated the process of monocyte differentiation to macrophages, which is important for atherosclerosis development." (PMID 27777559, 2016). "However, the overall effects of dapagliflozin on atherosclerosis in DM and the potential benefits involved, for example, their effects on IL-1β and IL-18 cytokines and NLRP3 inflammasome systems, have not been evaluated." (PMID 28104929, 2016).
atherosclerosis (continued). "The expression of vascular inflammatory markers was assessed to further determine whether the elevation of SREBP-1 and NLRP3- and ASC-mediated production of IL-1β is pathologically relevant to vascular inflammatory process and endothelial dysfunction in atherosclerosis." (PMID 23825667, 2013). "However, a recent study also found that genetically crossing APOE mice to mice that lack NLRP3 does not diminish the severity or incidence of atherosclerosis." (PMID 23087690, 2012). "Thus, mtROS can activate the NLRP3-dependent pyroptosis pathway by inducing the oxidation of GSDMD, which damages cardiomyocytes and myocardial tissue, leading to various cardiovascular conditions, including cardiac hypertrophy, atherosclerosis, and myocardial reperfusion injury." (PMID 41300435, 2025). "Thus, the inhibition of caspase-1, NLRP3, or GSDMD in dyslipidemic and inflammatory contexts prevents endothelial pyroptosis and improves endothelial survival, thereby preserving vascular intima integrity, reducing vascular inflammation, and further attenuating the progression of atherosclerosis." (PMID 37894840, 2023). "Therefore, targeting NLRP3 alone may not be sufficient to fully modulate the inflammasome response in atherosclerosis." (PMID 37175869, 2023). "We therefore applied a nongenetic gain-of-function PCSK9-AAV8 atherosclerosis model to address the question whether atherosclerosis development depends on IL-1α or the NLRP3 inflammasome and whether IL-1α expressed at the cell surface is involved in the development of atherosclerosis." (PMID 37701434, 2023). "The NLRP3 inflammasome and IL-1 family of cytokines are central to the pathologic response to injury and represent a key pathogenetic mechanism in the formation, progression, and complication of atherosclerosis and the myocardial response to ischemic and non-ischemic injuries." (PMID 36110200, 2022). "Thus, GsdmD may play role in Nlrp3 inflammasome mediated dampening of RCT and in promoting the progression of atherosclerosis, either by virtue of increasing IL-1β release from live inflamed immune cells or by promoting pyroptotic cell death in advanced atherosclerotic plaques." (PMID 34395445, 2021). "The NLRP3 inflammasome in subcutaneous adipose tissue (SAT) from patients who underwent heart device implantation and coronary angiography, may be involved in the development of atherosclerosis and is directly connected with the severity of coronary atherosclerosis." (PMID 31354731, 2019). "The absence of NLRP3 and the adaptor protein ASC or IL-1α/β in bone marrow cells drastically reduces atherosclerosis, indicating that cholesterol-induced inflammasome activation plays an important role in atherogenesis." (PMID 40305368, 2025). "Initial studies in NLRP3/ApoE, ASC/ApoE and caspase-1/ApoE double knockout mouse models failed to reveal significant effects on atherosclerosis, plaque macrophage numbers or stability." (PMID 36459456, 2022). "Though Nlrp3/AIM2 and IL-1β nexus is an emerging atherogenic pathway, the direct role of GsdmD in atherosclerosis is not yet fully clear." (PMID 34395445, 2021). "Mice lacking NLRP3 inflammasome-related genes, e.g., NLRP3, ASC, and IL-1β, had markedly decreased atherosclerosis compared to wild-type mice in response to a high-cholesterol diet, indicating the important roles of the NLRP3 inflammasome in atherosclerosis." (PMID 30186288, 2018). "Moreover, dapagliflozin inhibited the expression of NLRP3, ASC, caspase-1, IL-1β, and IL-18 in DM mice, and such expression was also decreased in the nondiabetic atherosclerosis model (not statistically significant)." (PMID 28104929, 2016).
colitis (601 papers, 2013 to 2026). Inflammation of the colon. "Research indicates that a deficiency in the NLRP3 inflammasome increases susceptibility to experimental colitis in mice." (PMID 41149694, 2025). "Myeloid Vangl2-deficiency in mice results in increased susceptibility to DSS-induced colitis due to the overactivation of NLRP3 inflammasome." (PMID 39899477, 2025). "Previous studies have demonstrated that NLRP3 knockout (NLRP3-/-) mice exhibit increased susceptibility to colitis, likely due to alterations in gut microbiota composition and subsequent changes in β-defensin levels." (PMID 40433382, 2025). "Kynurenic acid, a colitis-associated endogenous regulator, induces autophagy-dependent degradation of NLRP3 in macrophages via the kynurenic acid/G-protein-coupled receptor 35 (GPR35) axis." (PMID 40842999, 2025). "The NLRP3 inflammasome has been recognized as a pivotal mechanism underlying intestinal inflammation in the DSS-induced colitis model." (PMID 40883849, 2025). "NLRP3 inflammasomes protect colonic mucosa during acute colitis, and their deficiency exacerbates chemically induced colitis-associated CRC." (PMID 41267084, 2025). "Myeloid VANGL2 deficiency exacerbates the progression of DSS-induced colitis in mice and specifically enhances the activation of NLRP3 inflammasome in macrophages." (PMID 39899477, 2025). "Genetic factors affect IBD by regulating the activation of inflammasomes; the CARD8 gene inhibits NLRP3 inflammasome assembly, interacts with NLRP3, and inhibits NLRP3 oligomerization caused by variant V44I that exacerbates colitis and Crohn’s disease." (PMID 41149694, 2025). "This study examines α7nAChR and NLRP3 expression in gastric and colorectal cancers, colitis, and normal tissues to clarify pathogenic mechanisms and identify therapeutic targets." (PMID 41003004, 2025). "The body weight of WT and Nlrp3-/- mice decreased significantly due to colitis, with Nlrp3-/- mice showing less weight loss than WT mice." (PMID 40362256, 2025). "NLRP3-specific inhibitor MCC950 effectively alleviates DSS-induced colitis in VANGL2 deficient mice." (PMID 39899477, 2025). "The role of the NLRP3 inflammasome in protecting against colitis-associated colon cancer has been well established, and it helps to resolve inflammation and prevent the development of cancer." (PMID 38486106, 2024). "The number of tumors in the colon was significantly reduced in the GLB and NLRP3-KO groups compared to the CTRL cohort, suggesting that GLB treatment and NLRP3 deficiency had suppressed the development of colorectal tumors associated with colitis." (PMID 39519191, 2024). "In the DSS-induced colitis model, NLRP3 deficiency resulted in severe colitis characterized by significant weight loss and colon shortening." (PMID 39519191, 2024). "The inflammasome has a protective effect on colitis-associated colorectal cancer, and in particular NLRP3 is closely associated with colorectal cancer." (PMID 39325798, 2024). "The anti-tumor role of inflammasomes in colitis-associated CRC such as maintaining epithelial cell integrity by NLRP3 inflammasomes in IBD has been extensively studied." (PMID 39062587, 2024). "Deficiencies in different components of the NLRP3 inflammasome can lead to increased colitis and colon cancer; hence, the inflammasome can operate as a suppressor of inflammation and tumor progression." (PMID 39684769, 2024). "The research by Chung and colleagues suggests that using inactivated E. faecalis as a probiotic to reduce NLRP3-mediated colitis and inflammation-associated colon carcinogenesis is a feasible and safe option." (PMID 39323474, 2024). "were the first to postulate that the ADP/P2Y1-axis activates the NLRP3-inflammasome in mice and implicated its relevance in experimental colitis." (PMID 37410223, 2024). "Atractylenolide (ATR I) suppressed NLRP3 inflammasome activation in colitis-associated colorectal cancer via the inhibition of mitochondrial damage." (PMID 39684769, 2024).